KLHL5 (kelch like family member 5)
Tractability: Small molecule: it belongs to a druggable protein family. Antibody: its Gene Ontology location is reachable by antibodies, with high confidence. PROTAC: ubiquitination databases record sites on it.
Gene: Protein-coding gene on chromosome 4 (39,044,721 to 39,126,857, forward strand). Ensembl gene ENSG00000109790.
Subcellular location: Cytoplasm, cytoskeleton
Subcellular location (Human Protein Atlas): Microtubules; Plasma membrane
Pathways (Reactome):
Immune System: Antigen processing: Ubiquitination & Proteasome degradation
Metabolism of proteins: Neddylation
Gene Ontology:
Molecular function: protein binding; ubiquitin-like ligase-substrate adaptor activity
Biological process: proteasome-mediated ubiquitin-dependent protein catabolic process
Cellular component: microtubule cytoskeleton; Cul3-RING ubiquitin ligase complex; cytoplasm; cytosol; cytoskeleton
Genetic constraint (gnomAD): Loss-of-function variants: 41 observed, 74.8 expected, observed/expected ratio (o/e) 0.55, 90% interval 0.43 to 0.71. The upper end of that interval is the gene's LOEUF score, 0.71, which puts it in group 2 of 6, group 1 being the genes least tolerant of losing a copy. Missense variants: 706 observed, 878.79 expected, observed/expected ratio (o/e) 0.8, 90% interval 0.75 to 0.86. Synonymous variants: 254 observed, 305.61 expected, observed/expected ratio (o/e) 0.83, 90% interval 0.75 to 0.92.
Homologues: Orthologues: macaque KLHL5 (99% identical), dog KLHL5 (99% identical), guinea pig KLHL5 (99% identical), chimpanzee KLHL5 (98% identical), rat Klhl5 (97% identical), mouse Klhl5 (97% identical), pig KLHL5 (97% identical), rabbit KLHL5 (91% identical), tropical clawed frog klhl5 (86% identical), zebrafish klhl5 (75% identical), Drosophila melanogaster CG17754 (47% identical). Paralogues in human: KLHL1 (66% identical), KLHL4 (65% identical), KLHL20 (36% identical), KLHL17 (36% identical), KLHL3 (33% identical), KLHL2 (33% identical), KLHL8 (31% identical), KEAP1 (30% identical), KLHL28 (30% identical), KLHL12 (29% identical), KLHL18 (28% identical), IPP (27% identical), and 42 more.
Diseases named in the same sentence as KLHL5 in open-access papers:
KLHL5 is named in the same sentence as 20 diseases in open-access papers, as found by Europe PMC text mining. Sharing a sentence is not in itself a finding about the gene and the disease. The quoted sentences say what the papers report.
gastric cancer (2 papers, 2020 to 2024). A primary or metastatic malignant neoplasm involving the stomach. "In this study, we selected KLHL5 to investigate its potential as a biomarker of prognosis and explore its underlying mechanism in gastric cancer." (PMID 33363208, 2020). "This reveals that KLHL5 is an important modulator in gastric cancer immune infiltration, potentially inducing tumor macrophage infiltration." (PMID 33363208, 2020). "Especially, KLHL5 mRNA expression was upregulated and correlated with poorer overall survival and progression-free survival in gastric cancer." (PMID 33363208, 2020). "Previous studies have found that METTL3 may promote EMT in GC by regulating the m6A level of KLHL5, leading to the distant metastasis of gastric cancer, especially lung metastasis." (PMID 39195675, 2024). "Thus, KLHL5 is identified as a reliable predictor of prognosis in gastric cancer patients." (PMID 33363208, 2020). "Moreover, KLHL5 was found to be significantly associated with Tregs and exhausted T-cell biomarkers, suggesting that KLHL5 may have an impact on escape of immune surveillance in gastric cancer, which needs further research to be expounded." (PMID 33363208, 2020). "This hints that KLHL5 may modulate T lymphocyte immunity in gastric cancer." (PMID 33363208, 2020). "KLHL5 overexpression in gastric cancer was correlated with enhanced dendritic cell infiltration in TIMER; on par with this, the expression of dendritic cell markers was also related with KLHL5 level in GEPIA." (PMID 33363208, 2020). "Meanwhile, KLHL5 was closely related with level of CD8+ T cells (cor = 0.237, P = 4.19e−06), CD4+ T cells (cor = 0.459, P = 4.19e−06), and macrophage (cor = 0.534, P = 1.22e−28), neutrophil (cor = 0.297, P = 5.1e−09), and dendritic cell (cor = 0.469, P = 9.48e−22) infiltration in gastric cancer." (PMID 33363208, 2020).
malignant melanoma (2 papers, 2018 to 2020). "KLHL5 knockdown decreased viability versus scramble control in all five cell lines with the most profound decrease in the melanoma cell line MEL-2." (PMID 30647843, 2018).
adrenocortical carcinoma (1 paper, 2020). "The results showed that there was a significant correlation between KLHL5 overexpression and a better OS and DFS in KIRC, but a more unfavorable OS and DFS in ACC (adrenocortical carcinoma)." (PMID 33363208, 2020).
cholangiocarcinoma (1 paper, 2020). A carcinoma that arises from the intrahepatic biliary tree (intrahepatic cholangiocarcinoma) or from the junction, or adjacent to the junction, of the right and left hepatic ducts (hilar cholangiocarcinoma). "Next, to further substantiate the relation between KLHL5 and immunocyte level, TIMER site and GEPIA were surveyed to examine the correlation between immunocyte gene makers and KLHL5 expression in gastric adenocarcinoma, with cholangiocarcinoma serving as the control." (PMID 33363208, 2020). "The results showed that KLHL5 expression was not correlated with tumor purity (P = 8.28e−01), B cell (P = 7.92e−01), CD4+ T lymphocytes (P = 2.32e−01), CD8+ T lymphocytes (P = 6.33e−01), macrophages (P = 4.96e−01), or dendritic cell (P = 6.16e−01) level in cholangiocarcinoma." (PMID 33363208, 2020).
gastric tumors (1 paper, 2020). "Oncomine data showed that the overexpression of KLHL5 was identified in many malignancies like brain, cervical, breast, esophageal, colorectal, and gastric tumors, whereas it was downregulated in cancer tissues of bladder, lung, prostate, and so on in some microarrays." (PMID 33363208, 2020). "Also, survival analysis of Kaplan–Meier plotter database showed that the KLHL5 overexpression foreboded disappointing OS and PFS in gastric neoplasm patients." (PMID 33363208, 2020).
Obesity (1 paper, 2022). Accumulation of substantial excess body fat. "Seven of the genes were downregulated by obesity and reversed by VSG specific weight loss including Ido1, Aldoc, Tmem125, Dgki, Slc7a4, Msc, and Ephb3, while four were inversely regulated with obesity elevating Klhl5, Nek6, Arhgap20, and Hp." (PMID 35775614, 2022).
renal carcinoma (1 paper, 2018). A carcinoma arising from the epithelium of the renal parenchyma or the renal pelvis. "While KLHL5 expression shows marginal dysregulation in cancer, other KLHLs exhibit significant dysregulation in all cancer types, and exceptionally in renal carcinomas." (PMID 30647843, 2018).
skin cutaneous melanoma (1 paper, 2020). "In addition, overexpression of KLHL5 was correlated with a worse OS in LUAD and MESO, but with a better OS in SKCM (skin cutaneous melanoma)." (PMID 33363208, 2020).
Stomach adenocarcinoma (1 paper, 2020). "In our study, we aim to envision the landscape of KLHL5 and its relationship with patient prognosis in cancers, and try to shed some light on the underlying mechanism of KLHL5 functions in cancers, particularly in gastric adenocarcinoma." (PMID 33363208, 2020).
cancer (3 papers, 2018 to 2023). A tumor composed of atypical neoplastic, often pleomorphic cells that invade other tissues. "The potential of KLHL5 as a prognostic or diagnostic cancer marker was compared to other KLHLs through a pan-cancer study of The Cancer Genome Atlas (TCGA) tumor groups." (PMID 30647843, 2018). "The variant expression level of KLHL5 in the same cancer from different databases or even the same databases may be attributed to different data collection approaches and diversified molecular functions." (PMID 33363208, 2020). "KLHL5 also had a significant expression decrease in renal papillary (AUC = 0.899), but largely the diagnostic value of expression differences as indicated by AUC curves from these cancer types was underwhelming." (PMID 30647843, 2018). "KLHL5, also known as Kelch-like protein 5, has been shown to be involved in the development of cancer, particularly in the regulation of cell proliferation and apoptosis." (PMID 36816032, 2023). "In this study, we mined Oncomine and GEPIA database for the landscape of KLHL5 in 33 types of cancers, and observed varied expression of KLHL5 between tumor tissues and benign controls in cancers." (PMID 33363208, 2020). "Another finding in our study is that the level of inflammatory infiltrates is correlative of KLHL5 in different types of cancers, especially in STAD." (PMID 33363208, 2020). "After surveying the database, we found there was a significant correlation between KLHL5 with tumor purity in 23 cancers." (PMID 33363208, 2020). "Although its full functions remain uncertain, it is clear that KLHL5 knockdown inhibits cell proliferation in certain cancer cell lines." (PMID 33363208, 2020). "Here, we report KLHL5 expression correlates with patient clinical outcomes in multiple cancer types." (PMID 33363208, 2020). "The potential clinical implications of KLHL5 were explored using a pan-cancer study of KLHL expression in fifteen cancers from The Cancer Genome Atlas (TCGA)." (PMID 30647843, 2018). "Cell cycle inhibitors that inhibited checkpoint, Aurora Kinase, or Cdks were also among compounds that observed synergistic anti-cancer effect with KLHL5 knockdown." (PMID 30647843, 2018). "KLHL5 knockdown decreased the proliferation and viability of cancer cells and sensitized cancer cells to numerous anti-cancer drugs." (PMID 30647843, 2018). "The interaction of KLHL5 with anti-cancer compounds that target cell cycle processes is consistent with the known and suspected functions of KLHL5 as visualized from the STRING database." (PMID 30647843, 2018). "From our study of KLHL5 knockdown, the reduction of KLHL5 expression led to a decrease in cancer cell proliferation and viability." (PMID 30647843, 2018). "This study explores the relationship of expression of KLHL member, KLHL5, with the pharmacologic effect of anti-cancer drugs." (PMID 30647843, 2018). "What is more, KLHL5 expression was associated with the immunocyte level of B cell in 21 types, CD8+ T cell in 27 types, CD4+ T cell in 25 types, macrophage in 33 types, dendritic cell in 31 types, and neutrophil in 33 cancer types." (PMID 33363208, 2020). "This implies that inhibiting or regulating KLHL5 could be a potential method of sensitizing cancer cells to specific drugs." (PMID 30647843, 2018). "Because of this relationship to anti-cancer therapeutics, KLHL5 upregulation could theoretically lead to resistance to therapeutics as a drug resistance gene." (PMID 30647843, 2018). "To better understand the full prospect of the relationship between KLHL5 expression and patient survival in 33 tumor types, we inquired into the GEPIA for survival plots in each cancer type." (PMID 33363208, 2020). "Among the ~20,000 anti-cancer compounds in the NCI dataset, over 1600 compounds had a negative correlation less than -0.400 between drug effect and KLHL5 expression." (PMID 30647843, 2018).
cancer (continued). "Cellular viability was observed with treatment of 346 anti-cancer compounds in the presence and absence of KLHL5 siRNA knockdown." (PMID 30647843, 2018).
tumor (2 papers, 2018 to 2020). "The correlation between KLHL5 and gene markers associated with immunocyte subsets was extracted and results were adjusted according to the tumor purity." (PMID 33363208, 2020). "More studies are needed to confirm KLHL5 function in dendritic cell regulation and tumor metastasis in the future." (PMID 33363208, 2020). "This hinted that KLHL5 is a key factor in tumor dendritic cell penetration." (PMID 33363208, 2020). "Furthermore, KLHL5 expression correlated significantly with OS and PFS in subgroups divided by clinicopathological features, such as gender, stage, tumor stage, and node stage excluding node free or distant metastasis." (PMID 33363208, 2020). "High level of KLHL5 in STAD is related with a poorer OS and DFS; particularly, it is significantly correlated with prognosis in lymph node–positive patients, which indicates that KLHL5 is a potential biomarker of tumor metastasis." (PMID 33363208, 2020). "Also, the correlation between KLHL5 and stage N2 has the highest ratio of OS and PFS except for stage 2 and tumor size stage 4." (PMID 33363208, 2020).
blood cancer (1 paper, 2020). "Across the TCGA database, the expression of KLHL5 correlates with prognosis in mammary, brain, soft tissue, colorectal, lung, ovarian, and blood cancer." (PMID 33363208, 2020).
KLHL5 also shares sentences with these, for which no sentence is quoted: breast carcinoma (1 paper); ciliopathy (1); esophageal carcinoma (1); head and neck squamous cell carcinoma (1); lung adenocarcinoma (1); lung squamous cell carcinoma (1); lymphoma (1); ovarian carcinoma (1).